MIR4458HG (MIR4458 host gene)
Gene: Long non-coding RNA gene on chromosome 5 (8,450,701 to 8,486,930, forward strand). Ensembl gene ENSG00000247516.
Diseases named in the same sentence as MIR4458HG in open-access papers:
MIR4458HG is named in the same sentence as 1 disease in open-access papers, as found by Europe PMC text mining. Sharing a sentence is not in itself a finding about the gene and the disease. The quoted sentences say what the papers report.
tumor (1 paper, 2024). "In contrast, six genes known to inhibit cell proliferation and tumor growth were overexpressed in d-HGP: SIRT6, MPC2, MIR4458HG, ST20-AS1, SREBF2, MRPL40." (PMID 38548918, 2024).